IL1B (interleukin 1 beta)
Diseases named in the same sentence as IL1B in open-access papers (continued):
Sharing a sentence is not in itself a finding about the gene and the disease.
Arthritis (continued). "We have shown that celastrol inhibits both interleukin (IL)-1β and tumour necrosis factor (TNF), which play an important role since the early phase of RA, and has significant anti-inflammatory and anti-proliferative properties in an adjuvant-induced rat model of arthritis (AIA)." (PMID 26658436, 2015). "Therefore, similar to the positive drug indomethacin, EMI may be served as an antigouty arthritis agent mediated by inhibition of cytokines expression such as TNF-α and IL-1β." (PMID 23304232, 2012). "Western blotting revealed that recombinant IL-12 increased pro-IL-1β expression in joint cells from WT mice with arthritis in the presence or absence of LPS, suggesting that TLR4-mediated IL-12 regulates the production of pro-IL-1β in joint cells, rather than its cleavage." (PMID 23036692, 2012). "We did, however, measure equal levels of IL-1β in the mBSA-challenged and the PBS-challenged paws on days 1 and 3 after DTH-arthritis induction, and these measurements could point toward a direct effect of the anti-CII antibodies on the production of this cytokine." (PMID 22676339, 2012). "Another characteristic of the K/BxN transfer model is that it allows us to focus on the effector phase mechanisms of arthritis that are dependent on neutrophils, macrophages, mast cells, and inflammatory mediators, especially IL-1β, but independent of T cells and B cells." (PMID 21190566, 2010). "The upregulated expression of TNF-α, IL-1α, IL-1β, IL-4R, P-selectin, MIP-1α (CCL3), MCP-1 (CCL2), NOS2 and NOS3 demonstrated in the present study is in agreement with previous observations of the dependency of the rat SCW-induced arthritis model on these mediators." (PMID 15642130, 2005). "Moreover, magnolol was able to reverse the IL-1β-induced increase in the expression of genes related to inflammation [IL-6, cyclooxygenase-2 (COX-2), matrix metalloproteinases (MMPs), etc.] in a rat arthritis model by blocking the AP1 signaling pathway, thereby alleviating arthritis." (PMID 39491001, 2024). "Traditional arthritis treatments that include steroids, non-steroidal anti-inflammatory drugs (NSAIDs), and biological agents such as antagonists of TNF-α and interleukin-1 beta (IL-1β) have limited efficacies and are associated with several unpleasant side effects." (PMID 39070788, 2024). "Therefore, although tea and tea polyphenols can neutralize the inflammatory effects of IL-1β and IL-6, they also effectively utilize TNF-α to play its basic function of regulating the uncontrolled proliferation of activated synovial fibroblasts to improve the functional status of arthritis joints." (PMID 37033930, 2023). "However, the comparison of Il1a−/−TTP−/− and Il1b−/−TTP−/− mice suggests that IL-1α might contribute more to the lack of fertility and to arthritis, whereas IL-1β plays a more critical role in the weight gain deficit." (PMID 32733464, 2020). "The present findings not only amplified the pivotal role of IL-1β and p38MAPK in CFA-induced arthritis modulated by long-term probiotics use with effective dosage, but also suggested that MOR may have another effectual target for arthritis management via probiotic treatment." (PMID 30719247, 2018). "In addition, the hedgehog antagonists, cyclopamine, KAAD-cyclopamine, SANT-1, and GANT61, did not display any significant inhibition of IL-1β-induced cartilage damage, despite previous reports suggesting a potential therapeutic role for hedgehog blockade in arthritis." (PMID 26705100, 2015). "This pathway seems not to contribute to the pathology of arthritis during the stages of flare-up and acute inflammation, but may well propagate chronic catabolic processes in a joint, even when IL-1β or TNF-α are not expressed at pathological levels or are captured pharmacologically." (PMID 23675204, 2010).
Arthritis (continued). "This research described the antioxidant (SOD3, CAT, GPX, ATOX1 and COX18) and immunological (IL-1α, IL-1β, IL-6, IL-10, TNFα, NCF4, NFKB, TMED, FCAMR and iNOS) genes in rams that had arthritis and those that did not." (PMID 40005882, 2025). "Among all genes tested, the expression levels of Cxcl1, Mcp1, Il-1b, and Il-6 were significantly upregulated in the DRG after arthritis remission whereas no significant changes in Tnfα mRNA expression in the DRG were observed." (PMID 35833115, 2022). "Although not statistically significant, the concentrations of TNF-α, IL-1β, and MDA tended to be lower in A77 1726-treated arthritis mice than in vehicle (DMSO)-treated animals." (PMID 28193225, 2017). "Indeed, this hypothesis was supported by our results, wherein Mcpt-6 gene expression as well as tryptase-like activity were upregulated 7 days after mBSA/IL-1β-induced arthritis to levels seemingly not counterbalanced by endogenous tryptase inhibitors, such as SPAG11B/C." (PMID 28587618, 2017). "Second, injection of LPS enhanced antibody-induced arthritis and the production of IFN-γ and IL-1β in the joints of WT mice, but not IL-12p35-/- mice." (PMID 23036692, 2012). "In humans, B. burgdorferi-induced IL-1β was partly NOD2-dependent, but the role of this PRR in the development of arthritis has never been demonstrated." (PMID 23148704, 2012). "It has not yet been determined whether adiponectin or IL-1β contributes more to the increased expression of these MMPs in arthritic joints, but the high concentration of adiponectin in joint fluids of patients with arthritis seems to contribute significantly to the joint degradation." (PMID 20804602, 2010). "In conclusion, our data demonstrate that in two genetic mouse models of arthritis, driven by either TNF or IL‐1β, musculoskeletal disease develops independent of the microbiota, independent of gut inflammation, but instead is driven by joint‐specific sterile factors." (PMID 37694693, 2023). "As might be expected, key pro-inflammatory cytokine USRs such as TNF, IFNG, IL6, and IL1B that were upregulated during CHIKV arthritis were downregulated (negative z-scores) in the ameliorated foot swelling seen in Gzma-/- mice." (PMID 35119362, 2022). "In addition, food-restriction led to a more profound decrease of mRNA expressions for anorexigenic factors (POMC, CART, IL-1β) and marked increase of mRNA expressions for orexigenic factors (NPY, AgRP) compared to the other dietary regimes with or without arthritis." (PMID 20953376, 2010).
osteoarthritis (649 papers, 2006 to 2026). A noninflammatory degenerative joint disease occurring chiefly in older persons, characterized by degeneration of the articular cartilage, hypertrophy of bone at the margins and changes in the synovial membrane. "These cells showed enrichment for several immune modulators including Il1b, a key cytokine implicated in osteoarthritis pathogenies and Csf1, a key regulator of monocyte to macrophage differentiation." (PMID 39752388, 2025). "These discoveries underscore the protective role of PD against IL-1β-induced cartilage damage associated with osteoarthritis in vitro, highlighting its potential therapeutic implications." (PMID 39840130, 2024). "The progression involves the NF-κB signaling pathway, triggered by IL-1β, affecting the enzymes linked with pathophysiology of osteoarthritis, including iNOS, PLA2, COX-2, prostaglandin E synthase 2 (PGE2 synthase), and MMPs." (PMID 39204123, 2024). "TNF-α, in combination with IL-1β, is recognized as a pivotal inflammatory cytokine implicated in the pathophysiological mechanisms observed during the progression of osteoarthritis." (PMID 39204123, 2024). "The expression of COL3A1 was associated with the increase of IL-1β in osteoarthritis and was also linked to immune cell infiltration." (PMID 37415178, 2023). "Leptin and interleukin-1 beta (IL-1β) are two extensively studied biomarkers associated with metabolic syndrome (MetS) and osteoarthritis (OA)." (PMID 37703108, 2023). "Mg can reduce the loss of type II collagen and glycosaminoglycan in osteoarthritis, and can inhibit the expression of interleukin-1β (IL-1β), Tumor Necrosis Factor-α (TNF-α), and matrix metalloproteinase 13 (MMP13) in osteoarthritis." (PMID 36546928, 2022). "The downregulation of AQP9 was observed in the cartilage cells, which would cause the decomposition-related genes of stimulating the IL-1β that is down-expressed in osteoarthritis." (PMID 35531067, 2022). "With regard to osteoarthritis (OA) an association with predisposition for hip radiographic osteoarthritis was described for the heterozygous and homoygous carriers of the IL-1B allele -511T." (PMID 36518750, 2022). "Step two: the chondrogenic WJ-MSCs were treated with 10 ng/ml IL-1β for 24 h to evaluate their susceptibility to an osteoarthritis-like phenotype." (PMID 33663609, 2021). "These recombinant yeasts downregulated IL-1β expression in macrophages, consequently leading to alleviation of the inflammation caused by osteoarthritis in a mouse model." (PMID 34592900, 2021). "This study investigated the potential of FA in suppressing IL‐1β‐induced degeneration of osteoarthritis chondrocytes and explored the molecular mechanism underlying this regulation." (PMID 34078001, 2021). "AGT was observed to have a strong association with the risk of osteoarthritis (OR 3.12, 95%CI: 1.88–5.19), which remained significant even after additional adjustment with BMI, TG, sleep, IL-6, IL-1β, and CRP levels (OR 2.73, 95%CI:1.63–4.72)." (PMID 34073132, 2021). "Oxidative stress-mediated activation of the Nod-like receptor protein 3 (NLRP3) inflammasome was also associated with increased expression of NRF2, HMOX1, and IL1B in humans with osteoarthritis." (PMID 34744798, 2021). "As for the second step of the strategy, the differentiated WJ-MSCs were treated with interleukin 1β (IL-1β) to mimic the susceptibility to osteoarthritis." (PMID 33663609, 2021). "Main pro-inflammatory cytokines implicated in these processes are Interleukin-1 beta (IL1β) and Tumor Necrosis Factor alpha (TNFα), and their targeted inhibition has shown amelioration of osteoarthritis symptoms in diseased animal models." (PMID 34356815, 2021). "Previous studies showed that high level of IL‐1β was associated with bone erosion and cartilage destruction in RA and manifested additional characteristics of osteoarthritis (OA) which included increased osteophyte complex form." (PMID 33939304, 2021).
osteoarthritis (continued). "Pro-inflammatory cytokines that cause the pathogenesis of degenerative joint diseases, including IL-1β, IL-6 and TNF-α, suppress the expression of these genes." (PMID 32030322, 2020). "The ability to block high IL-1β levels makes HR a useful candidate for osteoarthritis treatment, because in chondrocytes, high values of IL-1β are implicated in the osteoarthritis pathogenesis." (PMID 32899225, 2020). "Formation of the ternary IL-1β /IL-1R1/IL-1RAcP protein complex and its downstream signaling has been implicated in osteoarthritis pathology." (PMID 33614593, 2020). "Conditional deletion of Elf3 in mouse chondrocytes results in decreased IL-1β-mediated induction of Mmp13 and Nos2, and these mice undergo less cartilage loss in a model of osteoarthritis." (PMID 30200227, 2018). "IL-1ra can inhibit the activity of IL-1β, whereas IL-1β overexpression is associated with osteoarthritis progression." (PMID 30013563, 2018). "In the present study, we aimed to investigate the anti-inflammatory effect of SSa on IL-1β-stimulated human osteoarthritis chondrocytes and clarify the underling mechanism." (PMID 29179489, 2017). "Interleukin-1beta (IL-1β) is the principal cytokine linked to cartilage degradation in osteoarthritis (OA)." (PMID 21682898, 2011). "Several studies have found elevated levels of the cytokine IL-1β in synovial fluid samples obtained from TMJ patients with osteoarthritis, and elevated concentrations of IL-1β in synovial fluid have been implicated in joint cartilage destruction." (PMID 20204061, 2009). "In addition to Rac-1 activation, IL-1β-induced activation of RhoA has been associated with several types of chronic inflammatory disorders, including osteoarthritis (OA)." (PMID 41596581, 2026). "A previous study suggested that IL1B was a ferroptosis-related diagnostic marker in osteoarthritis." (PMID 39588389, 2024). "ANE could reduce the loss of extracellular matrix by inhibiting IL-1β/NF-κB pathway during osteoarthritis of mouse." (PMID 36899420, 2023). "In an in vitro osteoarthritis model caused by IL-1β, miR-320a expression was markedly reduced." (PMID 37507717, 2023). "NLRP3 inflammasome has been implicated in osteoarthritis pathological progression through secreting proinflammatory cytokines including IL-1β and tumor necrosis factor-alpha (TNF-a), producing cartilage degrading enzymes like MMP3 and aggravating synovial membrane inflammation." (PMID 35935815, 2022). "Interestingly, the ALE-related prevention of hepatic oxidative stress and lipid metabolism disorder observed in a mouse model of steatohepatitis was associated with a lower IL-1β expression that accounts for osteoarthritis onset." (PMID 34444810, 2021). "Yaotongning capsules (a KTBAM compound) promoted proliferation and glycosaminoglycan synthesis in IL-1β-induced chondrocytes and may have potential activity in treating chondrocyte degeneration caused by osteoarthritis." (PMID 31885673, 2019). "Inflammatory cytokine IL-1β via up-regulation of AQPs caused the abnormal metabolism of water transport and loss of the cartilage matrix in the chondrocytes, and ultimately exacerbated the pathogenesis of early osteoarthritis." (PMID 31404098, 2019). "This compound has anti-inflammatory, anti-oxidative, and anti-cancer effects; however, the mechanism underlying the effects of genistein on IL-1β-stimulated human osteoarthritis (OA) chondrocytes remains unknown." (PMID 31137797, 2019). "Furthermore, a preinfectious joint damage, which was defined as any lesion including osteoarthritis, predisposed to higher intra-articular IL-1β concentrations indicating a higher degree of inflammation." (PMID 27688601, 2016). "Osteoarthritis (OA) is characterized by the loss of the balance between anabolic and catabolic responses of stimulated chondrocytes, driven locally by a series of cytokines of which IL-1β is regarded as the major factor." (PMID 25398247, 2014).
osteoarthritis (continued). "In contrast, interleukin 1β (IL-1β) is a cytokine and a key mediator of the inflammatory response that is associated with the activation of catabolic pathways in cartilage and chondrogenesis inhibition, leading the cartilage tissue to degradation and osteoarthritis (OA) development." (PMID 40143007, 2025). "Chondrocytes undergo glycolysis-associated metabolic switching after exposure to IL-1β or TNF in osteoarthritis, and this phenomenon contributes to chondrocyte injury during which the link between further inflammation and metabolic dysregulation may be exacerbated." (PMID 38264652, 2023). "Similarly, IL-1β, IL-8, and TNFα serum levels have been associated with osteoarthritis (OA)." (PMID 37445700, 2023). "In searching for the potential molecular mechanism underlying FA‐mediated suppression of IL‐1β‐induced osteoarthritis chondrocyte degeneration, we identified the SIRT1/AMPK/PGC‐1α signaling pathway might be an important cascade mediating the protective effects of FA." (PMID 34078001, 2021). "It is reported that some MCHF (Yaotongning capsule and Tougu Xiaotong capsule) promoted the proliferation and glycosaminoglycan synthesis in IL-1β induced chondrocytes and may have the potential activity on treating chondrocytes degeneration caused by osteoarthritis." (PMID 26609310, 2015). "For instance, EVs derived from IL-1β-activated fibroblast-like synoviocytes promote chondrocyte degeneration manifesting osteoarthritis-like pathological phenotypes." (PMID 41480405, 2026). "The persistent activation of both Rac-1 and RhoA by IL-1β contributes to chronic inflammatory diseases, including osteoarthritis (OA)." (PMID 41596581, 2026). "Similar stage-dependent miRNA changes have been reported in other degenerative conditions, such as osteoarthritis, where miR-186-5p downregulation increased IL-1β-induced chondrocyte injury through MAPK1 targeting." (PMID 41535614, 2026). "Osteoarthritis (OA) is an inflammatory bone disorder where IL-1β plays a central role in initiating inflammatory cascades." (PMID 41322309, 2025). "Osteoarthritis patients show increased concentrations of IL-1β in synovial fluid, cartilage, and subchondral bone." (PMID 40647239, 2025). "For example, RvD1 was reported to inhibit hemoglobin-induced JNK phosphorylation in microglial cells and suppress IL-1β–induced JNK1/2 activation in osteoarthritis chondrocytes." (PMID 41463049, 2025). "has unveiled that inhibiting the Nrf2/HO‐1 pathway results in increased activation of the NLRP3 inflammasome, along with upregulation of IL‐1β and IL‐18 expression in osteoarthritis." (PMID 41378869, 2025). "In vitro, the hydrogel protected chondrocytes from IL-1β-induced damage, while in vivo studies in an osteoarthritis model confirmed its ability to reduce cartilage degradation and promote chondrogenic regeneration." (PMID 40563345, 2025). "This includes lutikizumab (anti-IL1a and IL1b) for osteoarthritis, and COVA322, a bispecific TNF/IL17A antibody fusion protein studied in phase 1/2 in patients with stable chronic moderate-to-severe plaque Pso (stopped for safety reasons)." (PMID 40529150, 2025). "Another study indicated that miRNA-186 is associated with the development of inflammation via interleukin-1-beta (IL-1β) in osteoarthritis (OA)." (PMID 40869359, 2025). "Previous studies have also demonstrated that OMT decreased IL-1β-induced inflammation and extracellular matrix degradation in osteoarthritis models." (PMID 40569312, 2025). "Both TNFα and IL-1β are considered key inflammatory mediators in the pathogenesis of osteoarthritis." (PMID 40647239, 2025). "Human primary chondrocytes were collected and incubated with interleukin‐1 beta (IL‐1β) to simulate osteoarthritis (OA) in an in vitro environment to establish an OA chondrocyte model." (PMID 39905808, 2025).